OGG1 (8-oxoguanine DNA glycosylase)
Diseases named in the same sentence as OGG1 in open-access papers (continued):
Sharing a sentence is not in itself a finding about the gene and the disease.
infection (11 papers, 2011 to 2025). The state of being infected such as from the introduction of a foreign agent such as serum, vaccine, antigenic substance or organism. "Loss of OGG1 function markedly lowers viral RNA and protein levels, resulting in decreased viral titers in cultured cells and a mouse infection model." (PMID 39413143, 2024). "Administration of the small molecule TH5487, which inhibits OGG1 recognition of 8-oxoGua, decreases pathophysiological consequences of infections and ameliorates the associated tissue injury." (PMID 37600772, 2023). "Another BER-related protein, 8-oxoguanine glycosylase (OGG1), was associated with host cell chromatin 1 h after infection (1.80 fold change)." (PMID 33826673, 2021). "Indeed, renal Ogg1 mRNA expression were both significantly increased by 24 h after infection and associated with accumulation of both enzymes in the mitochondria." (PMID 24988481, 2014). "In this study, we found that RSV-infection generated oxidatively modified Gua lesions 8-oxoGua in promoters, and its reader, OGG1, impact antiviral gene expression." (PMID 37600772, 2023). "OGG1 also showed oxidation at its cysteine residues to sulfenic acid at all time points of infection, like those shown previously." (PMID 37600772, 2023). "Conversely, infection with a SOD2-expressing lentivirus (Tf-D-HKC8/↑SOD2) completely reversed this effect, whereas infection with an OGG1-expressing lentivirus (Tf-D-HKC8/↑OGG1) had little effect, compared with the control group (Tf-D-Scram/CTL)." (PMID 33423158, 2021). "In our model, OGG1 appears to be increased only after 1 h of infection, and then it returns to basal levels 6 h later." (PMID 33826673, 2021). "Relative to the uninfected control, OGG1 mRNA levels decreased to 57.5% and 47.9% at 24 and 36 h after infection, respectively." (PMID 30049996, 2018). "We then examined the effects of BoHV-1 productive infection on OGG1 expression by detection of OGG1 mRNA levels with qRT-PCR." (PMID 30049996, 2018). "Previously, in the liver, we found that transcription factors, NRF-1 and NRF-2, bind to consensus promoter sequences in Ogg1 suggesting this is part of larger program of mtDNA repair and mitochondrial biogenesis in response to infection." (PMID 24988481, 2014). "Deletion of the glycosylase genes Myh or Ogg1 led to decreased infection by HIV and FIV (Myh and HIV P = 0.004, Ogg1 and HIV P = 0.0011, Myh and FIV P = 0.013, Ogg1 and FIV P = 0.0001)." (PMID 21448280, 2011). "Also, at 6 h infection, we found a decrease in OGG1 mRNA levels compared to the control in HeLa cells." (PMID 33826673, 2021). "In addition, we observed that the VDAC1 mRNA levels did not change as a result of any of these treatments, while overexpression of SOD2 and OGG1 was shown to significantly increase each of the related mRNA levels, indicating successful infection." (PMID 33423158, 2021). "Kidneys from surviving mice were harvested at time zero (control), 24, or 48 hours after infection and evaluated for renal inflammation, oxidative stress markers, mtDNA content, and mitochondrial biogenesis markers, and OGG1 and UDG mitochondrial DNA repair enzymes." (PMID 24988481, 2014). "Infection of cells with deletion of the DNA polymerase gene Polß was similar to infection of Myh and Ogg1 null cells (HIV P<0.0001, MMLV P = 0.31, FIV P<0.0001), suggesting that the BER pathway significantly affects lentiviral infection but not gammaretroviral infection." (PMID 21448280, 2011). "We also investigated the mRNA relative expression of PARP-1, OGG1, and XRCC1, a protein involved in repairing DNA single-strand breaks, after 6 h of infection." (PMID 33826673, 2021). "Conversely, infection with a SOD2-expressing lentivirus (shHKDC1/↑SOD2) completely reversed this effect, whereas an OGG1-expressing lentivirus (shHKDC1/↑OGG1) had little effect, compared with the control group (CTL/EMP)." (PMID 33423158, 2021).
infection (continued). "The data obtained showed that at 7 dpi, the expression level of OGG1 remained significantly higher in case of single wtTBSV infection (no heat treatment) as compared to control plants." (PMID 41012677, 2025). "Later on, the fact that OGG1 is not increased at 6 h post-infection and the reduction on the frequency of FPG sensitive sites suggests that the repair of these lesions (possibly by BER) is performed rapidly in infected cells." (PMID 33826673, 2021). "Also, we analyzed the expression level of host protein OGG1 and TBSV genomic RNA in N. benthamiana after either single treatment with wtTBSV or combined effect (temperature + virus) at different time intervals post infection (3, 5 and 7 dpi)." (PMID 41012677, 2025). "Interestingly, the inhibition of HAZV primary infection did not correlate with the compounds’ OGG1 IC50-values as depicted by low Bravais–Pearson correlation score of 0.299." (PMID 33322045, 2020).
metabolic disease (11 papers, 2012 to 2024). A congenital disorder (due to inherited enzyme abnormality) or acquired (due to failure of a metabolically important organ) disorder resulting from an abnormal metabolic process. "Global deletion of OGG1 and common OGG1 polymorphisms render mice and humans susceptible to metabolic disease." (PMID 30291284, 2018). "Recent evidence demonstrates that the knockout of OGG1 leads to the supra-physiological accumulation of 8-oxoG; subsequently leading to anomalous immune responses and metabolic disorders." (PMID 29883433, 2018). "We have therefore investigated the role of OGG1 in the development of metabolic disease and report here a novel role for OGG1 in the maintenance of cellular and whole body energy balance." (PMID 23284747, 2012). "A previous study that reported on overexpression of the -2a isoform of OGG1 reported no protection against metabolic disease in this model." (PMID 30700008, 2019).
neurodegenerative disease (11 papers, 2015 to 2024). A disorder of the central nervous system characterized by gradual and progressive loss of neural tissue and neurologic function. "Here the authors reveal a role for HDAC1 in stimulating OGG1 activity to alleviate 8-oxoG lesions with implications in the aging brain and neurodegenerative diseases." (PMID 32424276, 2020). "Our findings link HDAC1 and OGG1 to oxidative DNA damage, neuronal gene expression, synaptic plasticity, and cognitive performance in brain aging and neurodegenerative disease, and highlight the therapeutic potential of pharmacological HDAC1 activation in aging and neurological disorders." (PMID 32424276, 2020). "OGG1 is a critical enzyme involved in the BER pathway, functioning as a repair enzyme and additionally participating in the development of neurodegenerative diseases and the processes of methylation and demethylation." (PMID 39519329, 2024).
kidney disease (4 papers, 2017 to 2025). "This study reviews the structure and biological functions of OGG1 and the regulatory mechanism of OGG1 in kidney disease." (PMID 36620083, 2022). "In particular, the epigenetic effects of OGG1 in kidney disease have gradually attracted widespread attention." (PMID 36620083, 2022). "In recent years, studies have found that OGG1 plays an important role in the progression of kidney diseases through repairing DNA, inducing inflammation, regulating autophagy and other transcriptional regulation, and governing protein interactions and functions during disease and injury." (PMID 36620083, 2022). "In addition, the possibility of OGG1 as a potential therapeutic target in kidney disease is discussed." (PMID 36620083, 2022). "Furthermore, significantly elevated sodium (Na), creatinine and IP level and lowered calcium (Ca) in the blood serum of DMBDD-initiated Ogg1−/− mice signified about the impaired kidney function or kidney disease." (PMID 28820464, 2017).
neurological disorders (4 papers, 2009 to 2024). "There are conflicting reports on brain OGG1 levels in ageing and neurological disorders: while a decreased OGG1 activity was observed in aged rat brain, its level was shown to increase in substantia nigra in PD." (PMID 25036887, 2014).
colon (3 papers, 2016 to 2022). "As lung, liver and colon tumors were observed in the DMBDD-treated Ogg1−/− mice that were found moribund during the study, effective number of animals used for the histopathological analysis included all mice." (PMID 28820464, 2017).
gynecological diseases (1 paper, 2025). "OGG1 plays a critical role in obstetric and gynecological diseases by influencing multiple pathological processes, including inflammation, vascular endothelial damage, and cell death." (PMID 40813502, 2025). "Although OGG1 plays a crucial role in various physiological and pathological processes, comprehensive reviews summarizing its mechanistic role in obstetric and gynecological diseases remain limited." (PMID 40813502, 2025). "OGG1 plays a critical role in several biological processes that contribute to the pathophysiology of obstetric and gynecological diseases, particularly through the regulation of immune and inflammatory responses, vascular endothelial damage, and cell death." (PMID 40813502, 2025). "Although we have made every effort to comprehensively review the available literature, we acknowledge that current studies specifically focusing on OGG1 in obstetric and gynecological diseases remain relatively limited." (PMID 40813502, 2025). "In this review, the mechanisms by which OGG1 regulates inflammation, vascular endothelial damage, and cell death are summarized, emphasizing its involvement and potential as a therapeutic target in obstetric and gynecological diseases." (PMID 40813502, 2025).
inflammation (1 paper, 2022). Aberrant reaction of the microcirculation characterized by movement of fluid and leukocytes from the blood into extravascular tissues. "However, 8-oxoguanine DNA glycosylase-1 (OGG1), a DNA repair protein may play a central role, as OGG1 deficiency decreases both innate and allergic inflammation." (PMID 36324676, 2022).
neurodevelopmental disorder (1 paper, 2023). A behavioral and cognitive disorder with onset during the developmental period that involves impaired or aberrant development of intellectual, motor, or social functions. "The OGG1- and EtOH-dependent associations provide a basis for more comprehensive mechanistic studies to determine the causal involvement of oxidative DNA damage and epigenetic changes in ROS-mediated neurodevelopmental disorders." (PMID 37759530, 2023). "This study demonstrated OGG1-dependent effects of in utero exposure of the fetal brain to physiological ROS levels, or to a single low dose of EtOH on epigenetic marks and gene expression in fetal brains, and postnatal behaviour, potentially relevant to neurodevelopmental disorders including FASD." (PMID 37759530, 2023).
psychiatric disorder (1 paper, 2025). A disorder characterized by behavioral and/or psychological abnormalities, often accompanied by physical symptoms. "Hence, it will be intriguing to explore the role of Ogg1 and Mutyh in epigenetic maintenance underlying neurocognitive and psychiatric disorders." (PMID 40779073, 2025).
reproductive diseases (1 paper, 2025). "However, comprehensive reviews detailing OGG1’s mechanistic roles in reproductive diseases remain scarce." (PMID 40813502, 2025).
OGG1 also shares sentences with these, for which no sentence is quoted: esophageal cancer (7 papers); Parkinson disease (5); esophageal squamous cell carcinoma (4); hearing loss (4); pterygium (4); xeroderma pigmentosum group D (4); bacterial infections (3); endometrial cancer (3); acute lymphocytic leukaemia (2); cardiomyopathy (2); chronic obstructive pulmonary disease (2); gynecologic cancer (2); invasive breast carcinoma (2); Lynch syndrome (2); neurotoxicity (2); oesophageal cancer (2); ovarian tumors (2); pancreatic cancer (2); small cell carcinoma (2); Splenomegaly (2); Age-related cataract (1); Allergy (1); amyotrophic lateral sclerosis (1); anxiety disorder (1); Arrhythmogenic right ventricular dysplasia (1); Arthritis (1); asthenozoospermia (1); autoimmune hemolytic anemia (1); Azoospermia (1); basal cell carcinoma (1).
A further 84 diseases each share a sentence with OGG1 in 1 paper.